POLR3A (RNA polymerase III subunit A)
Diseases named in the same sentence as POLR3A in open-access papers (continued):
Sharing a sentence is not in itself a finding about the gene and the disease.
leukodystrophy (continued). "POLR3-HLD, also termed 4H (Hypomyelination, Hypodontia, and Hypogonadotropic Hypogonadism) leukodystrophy, is caused by biallelic pathogenic variants in genes encoding subunits of the ubiquitous RNA polymerase III (Pol III) enzymatic complex (e.g., POLR3A, POLR3B, POLR1C, POLR3K, and POLR3D)." (PMID 39062571, 2024). "The mutations in POLR3A and POLR3B are the most frequently reported etiology for 4H leukodystrophy." (PMID 36042647, 2022). "In addition, an ever-increasing number of distinct mutations in the POLR3A, POLR3B, POLR1C and POLR3K subunits cause a spectrum of neurodegenerative diseases, which includes most notably hypomyelinating leukodystrophy." (PMID 34395528, 2021). "Mutations in genes encoding subunits of the transcription complex RNA polymerase III (POLR3), namely POLR3A, POLR3B, POLR1C, POLR3K and POLR3GL might cause a particular type of hypomyelinating leukodystrophies known as Pol III-related leukodystrophies." (PMID 33804237, 2021). "RNA polymerase III (POLR3)-related leukodystrophy is an autosomal recessive form of leukodystrophy caused by homozygous or compound heterozygous mutations of the RNA polymerase III subunit genes, including subunit A (POLR3A)." (PMID 33716926, 2021). "In conclusion, we suggest a new classification to patients carrying mutations in POLR3A, with neither leukodystrophy nor NPS features, which we propose designating as Neurodevelopmental Disorder with Regression, Abnormal Movements, and Increased Lactate." (PMID 33134517, 2020). "Mutations in the POLR3A gene cause POLR3A-related hypomyelinating leukodystrophy with or without oligodontia or hypogonadotropic hypogonadism (HLD7, OMIM: 607694) and neonatal progeroid syndrome (OMIM: 264090), both with high phenotypic variability." (PMID 33134517, 2020). "4H syndrome is a congenital hypomyelinating leukodystrophy characterized by hypodontia, hypomyelination and hypogonadotropic hypogonadism belonging to the Pol III-related leukodystrophies which arise due to mutations in the POLR3A or POLR3B gene." (PMID 29618326, 2018). "4H or POLR3-related leukodystrophy is inherited in an autosomal recessive fashion and is caused by mutations in one of three genes encoding RNA polymerase III (POLR3) subunits, that is, POLR3A, POLR3B, and POLR1C." (PMID 26478204, 2017). "To investigate the genetic aetiology of these unexplained cases, we performed exome sequencing in three cases with typical clinical and/or radiological features of POLR3-related leukodystrophy negative for POLR3A or POLR3B mutation." (PMID 26151409, 2015). "POLR3-related (or 4H) leukodystrophy is an autosomal recessive disorder caused by mutations in POLR3A or POLR3B and is characterized by neurological and non-neurological features." (PMID 26045207, 2015). "However, the actual frequency of extra‐pyramidal signs in POLR3A‐related leukodystrophy remains unknown." (PMID 39436788, 2024). "Several other recent studies that followed also reported variants in the POLR3A gene as being responsible for causing hypomyelination, hypodontia and hypogonadotropic hypogonadism, thus establishing a series of POLR3A gene variants to be associated with polymerase III-related leukodystrophy." (PMID 32982993, 2020). "In our previous work, we identified a hypomyelinating leukodystrophy-7 (HLD-7) family and detected the homozygous variation of POLR3A (NM_007055.4) gene c." (PMID 38561452, 2024). "Recessive mutations in the ubiquitously expressed POLR3A and POLR3B genes are the most common cause of POLR3-related hypomyelinating leukodystrophy (POLR3-HLD), a rare childhood-onset disorder characterized by deficient cerebral myelin formation and cerebellar atrophy." (PMID 31221184, 2019).
leukodystrophy (continued). "This first report of a missense mutation in subunits of Pol III in a vertebrate model organism thus demonstrates that bi-allelic mutations in Polr3a do not necessarily lead to leukodystrophy and/or cerebellar dysfunction in mice, and that Pol III vulnerability to mutations may vary between species." (PMID 28407788, 2017). "A subset of patients (∼5%) presenting with compatible clinical and/or radiological features of POLR3-related leukodystrophy have no detectible mutations in either POLR3A or POLR3B, suggesting that mutations in one or more additional genes may result in this presentation." (PMID 26151409, 2015). "Our assessment of the precursor stage suggested migration was unaffected when Polr3a, Polr3b, or Polr1c were downregulated, proposing that failure of OPCs to migrate to myelination sites is unlikely to explain the hypomyelination seen in POLR3-related leukodystrophy." (PMID 37179550, 2023).
hypogonadotropic hypogonadism (13 papers, 2015 to 2024). Abnormal ovarian or testicular function due to insufficient hormonal stimulation from the hypothalamic-pituitary axis. "POLR3A and POLR3B can be also associated to neurological or dental anomalies and isolated hypogonadotropic hypogonadism." (PMID 32982993, 2020). "POLR3A-related non-neurological findings typically described by others (i.e., acrocyanosis and dental abnormalities) were absent in all these Italian patients, with the exception of patient 4 who presented subclinical hypogonadotropic hypogonadism with low levels of FSH and LH." (PMID 34296356, 2022).
Ataxia (12 papers, 2020 to 2025). Ataxia refers to impaired coordination of voluntary muscle movement. "Biallelic variants in POLR3A have recently been identified as a common cause of sporadic and recessive ataxia and spastic paraparesis and treatment options remain scarce." (PMID 40248113, 2025). "Involvement of SCP in patients with POLR3A variants has previously been reported for the spastic-ataxia cohort and in four of eight atypical patients." (PMID 31940116, 2020). "POLR3A gene mutation can manifest with parkinsonism, dystonia, ataxia and tremor." (PMID 40917817, 2025). "The pathophysiology causing tremor may be very different even in this group of ataxias and possibly even within POLR3A-related diseases." (PMID 40248113, 2025). "In a large cohort of patients with a diagnosis of HSP or cerebellar ataxia of unknown origin mutations in POLR3A were identified in ~3.1% of cases, 80% of which were compound heterozygous for the c.1909 + 22G > A change." (PMID 33085208, 2020). "Furthermore, as recently observed in ataxia linked to both ultra-rare (i.e., POLR3A) and relatively more common (i.e., SPG7) genes, the presence of deep intronic mutations (not usually sought in TRP studies) might also explain these difficulties." (PMID 34445196, 2021). "Another report highlights the importance of an intronic variant in POLR3A, a gene previously associated with hypomyelinating leukodystrophy type 7, as a frequent cause of HSP and cerebellar ataxia." (PMID 33646413, 2021). "Compound heterozygous mutations in POLR3A were found in approximately 3.1% of index cases of HSP and cerebellar ataxia, with over 80% carrying the same intronic mutation (c.1909+22G>A) which activates a cryptic splice site." (PMID 33646413, 2021). "Currently, POLR3A, POLR3B, OTUD4, STUB1, PNPLA6, and RNF216 are all genes associated with CHH syndromes and cerebellar ataxia, with clinical manifestations that can vary and may present with infant or adult onset." (PMID 40508017, 2025). "In recent years, variants of POLR3A mutations without predominant ataxia have been reported which manifest as striatal disorders mostly presenting with dystonia and involvement of putamen, caudate and red nuclei." (PMID 36397839, 2022). "Similarly, hypomorphic mutations in POLR3A were reported as a cause of HSP and ataxia, however, other authors considered that this condition should be defined as a ‘POLR3-related disorder’ instead." (PMID 33646413, 2021). "Furthermore; in recent years, variants of POLR3A mutations without predominant ataxia have been reported as well." (PMID 36397839, 2022).
scleroderma (9 papers, 2014 to 2025). Scleroderma is a rare autoimmune connective tissue disorder characterized by abnormal hardening of the skin and, sometimes, other organs. "Some scleroderma patients have an antinuclear autoantibody to RNA polymerase III subunit C1 (RPC1) and in addition a cancer harboring a mutation in the RPCI POLR3A gene." (PMID 41403925, 2025). "Autoantibodies to RPC1, an RNA polymerase subunit encoded by the POLR3A gene, emerge in the sera of scleroderma patients with cancer in whom the POLR3A gene is mutated." (PMID 33506656, 2021). "The secondary occurrence of RPC1 autoantibodies and scleroderma in patients with a precancerous disease or cancer with somatically mutated POLR3A gene are examples." (PMID 33363034, 2020). "This process may reflect a broader mechanism relevant to multiple autoimmune diseases, as scleroderma patients with anti-RPA194 in addition to anti-POLR3A also have decreased cancer risk." (PMID 35040442, 2022). "Antibodies recognizing CCAR1 were present in 32% of patients with DM that were positive for anti–TIF1-γ in both cohorts and were found in only 1.5% of patients with scleroderma who possessed anti-POLR3A autoantibodies, suggesting good disease specificity." (PMID 35040442, 2022). "In several patients who had both scleroderma and cancer, genetic alterations of the POLR3A locus were found in the malignant cells, suggesting that POLR3A mutations triggered an adaptive antitumor immune response, which cross-reacted with normal tissue, causing autoimmune disease." (PMID 24860567, 2014). "Scleroderma is an autoimmune connective tissue disease in which patients make antibodies to a limited number of autoantigens, including the RNA polymerase III subunit, encoded by the POLR3A gene." (PMID 24860567, 2014). "A similar scenario has been described for patients with paraneoplasic scleroderma, in whom genetic alterations of the POLR3A locus and resulting T and B cell responses against the POLR3A gene product were detected in 75% of tumors but were absent from control tumors." (PMID 32655545, 2020).
Wiedemann-Rautenstrauch syndrome (8 papers, 2020 to 2025). Wiedemann-Rautenstrauch syndrome is a very rare disorder with features of premature aging recognizable at birth, decreased subcutaneous fat, hypotrichosis, relative macrocephaly and dysmorphism. "Wiedemann-Rautenstrauch Syndrome is a heterogeneous disorder caused by a pathogenic variant found in one of a few genes, including POLR3A, FBN1, CAV1, and SLC25A24." (PMID 40440483, 2025). "Wiedemann-Rautenstrauch syndrome (neonatal progeroid syndrome) is an ultra-orphan disease from the group of premature aging syndromes with an autosomal recessive type of inheritance associated with mutations in the POLR3A, POLR3B, and POLR3GL genes encoding RNA polymerase III." (PMID 38796765, 2023). "Biallelic alterations in POLR3A also result in Wiedemann-Rautenstrauch Syndrome (WRS), a variant of neonatal progeroid syndrome characterized by growth restriction, macrocephaly, and lipodystrophy." (PMID 36710885, 2022). "Two different conditions are associated with POLR3A mutations: HLD7 (OMIM: 607694) and neonatal progeroid syndrome (NPS, OMIM: 264090)." (PMID 33134517, 2020).
spastic ataxia (7 papers, 2020 to 2024). "In conclusion, a specific combination of biallelic POLR3A mutations with the c.1909+22G>A variant typically causes spastic ataxia but it can also manifest as generalised dystonia with prominent upper limb tremor that is DBS responsive." (PMID 38700104, 2024). "In summary, we describe the clinical course of a 75‐year‐old man with compound heterozygosity in POLR3A for the c.1909 + 22G>A allele, which has been associated with an adolescent‐to‐adult‐onset spastic ataxia." (PMID 34753215, 2022). "Adolescent‐to‐adult‐onset spastic ataxia linked to compound heterozygosity for an intronic mutation (c.1909 + 22G>A) in POLR3A has now been reported in several individuals and families." (PMID 34753215, 2022). "In this report, a man with adult‐onset spastic ataxia was found to have two pathogenic variants in POLR3A: c.1051C>T (p.Arg351*) and c.1909 + 22G>A (p.Y637Cfs*14)." (PMID 34753215, 2022). "Recently, a milder phenotype consisting of late-onset spastic ataxia has been suggested to be specific to an intronic mutation (c.1909 + 22G > A) in the POLR3A gene." (PMID 34296356, 2022). "We provide the first neuropathological evidence to support the role of these variants in the pathogenesis of spastic ataxia and expand the phenotypic description of POLR3A‐related disorders." (PMID 34753215, 2022). "Here, we present a series of 10 patients from 8 unrelated families with POLR3A-related late-onset spastic ataxia, all presenting with the c.1909 + 22G > A variant in compound heterozygosity, and discuss genotype–phenotype correlations in this cohort." (PMID 34296356, 2022). "POLR3A‐related disorders encompass neonatal progeroid syndrome, childhood‐onset hypomyelinating leukodystrophies to adult‐onset spastic ataxia." (PMID 38700104, 2024). "Here, we report the clinical course and neuropathologic features of the brain and spinal cord from a 75‐year‐old man with adult‐onset spastic ataxia, being a compound heterozygous POLR3A carrier." (PMID 34753215, 2022). "While the present report demonstrates some shared clinical and neuropathological features of late‐onset, POLR3A‐related spastic ataxia and Friedreich's ataxia, there are also some notable differences." (PMID 34753215, 2022).
Cerebellar atrophy (6 papers, 2015 to 2024). Cerebellar atrophy is defined as a cerebellum with initially normal structures, in a posterior fossa with normal size, which displays enlarged fissures (interfolial spaces) in comparison to the foliae secondary to loss of tissue. "Cerebellar atrophy is typically progressive and has been reported in up to 80% of cases according to the literature, although certain authors have suggested that it may be less frequently observed in patients with POLR3A variants." (PMID 39436788, 2024). "However, cerebellar atrophy and corresponding clinical symptoms were evident in these individuals, contrary to the observations in Polr3a KI/KI and KI/KO mice." (PMID 28407788, 2017). "Cerebellar atrophy was found almost in all patients with 4H syndrome, but the cerebellar anomalies were more severe in patients with POLR3B while the pattern of hypomyelinization was more evident in the MRI of POLR3A mutated patients." (PMID 26204956, 2015). "When patients have corresponding symptoms or signs, and there are diffuse hypomyelination and cerebellar atrophy on craniocerebral imaging, clinicians should highly doubt the possibility of POLR3-HLD and consider the sequencing of POLR3A and POLR3B genes in time." (PMID 38561452, 2024).
Dystonia (4 papers, 2020 to 2025). An abnormally increased muscular tone that causes fixed abnormal postures. "Deep brain stimulation of the globus pallidus has been reported to provide beneficial effects in individuals with POLR3A pathogenic variants presenting with parkinsonism and dystonia." (PMID 40917817, 2025). "In this report, we present a 6‐year‐old boy with a history of developmental regression, seizure, and dystonia from the age of two, who was diagnosed as a phenotypic variant of POLR3A mutation through whole‐exome sequencing." (PMID 36397839, 2022). "A new presentation of POLR3A gene mutation presenting as developmental regression, seizure and dystonia in a 6‐year‐old boy associated with striatum involvement in the brain MRI." (PMID 36397839, 2022). "Three patients with variants in POLR3A, an atypical presentation with dystonia, and MR involvement of putamen and caudate nucleus (striatum) and red nucleus have previously been reported." (PMID 31940116, 2020). "Since POLR3A gene mutations manifest predominantly as a movement disorder pharmacological approach might be considered as a first line treatment for tremor, dystonia and parkinsonism, nonetheless with a modest and transient response over time." (PMID 40917817, 2025).
Hypomyelinating leukodystrophy 7 (4 papers, 2019 to 2024). "Hypomyelinating leukodystrophy 7 (HLD7) is an autosomal recessive oligodendroglial cell-related myelin disease, which is associated with some nucleotide mutations of the RNA polymerase 3 subunit a (polr3a) gene." (PMID 35076634, 2021).
systemic sclerosis (4 papers, 2022 to 2025). A chronic disorder, possibly autoimmune, marked by excessive production of collagen which results in hardening and thickening of body tissues. "Similar findings have been reported in the polymerase (RNA) III subunit A (POLR3A) locus encoding RPC1 in tumour DNA from autoantibody positive patients with systemic sclerosis, but not in patients without autoantibodies to RPC1, or in peripheral blood." (PMID 35693792, 2022). "In BLM-induced systemic sclerosis mice, an increase in cytoplasmic DNA was observed, which promoted the translocation of RNA polymerase III A (POLR3A) and activated the POLR3A/STING pathway." (PMID 36545321, 2022).
encephalitis (3 papers, 2019 to 2022). An acute inflammatory process affecting the brain parenchyma. "Mutations in the POLR3A, POLR3C, POLR3E and POLR3F subunits are associated with susceptibility to varicella zoster virus-induced encephalitis and pneumonitis." (PMID 34395528, 2021). "Although only one of the POLR3A alleles is mutated, a new association between heterozygous mutations in POLR3A and susceptibility to varicella-zoster virus (VZV) infection (including encephalitis) was described recently." (PMID 31836009, 2019).
Tremor (3 papers, 2024 to 2025). An unintentional, oscillating to-and-fro muscle movement about a joint axis. "Alternatively, the network involved in the generation of the tremor in POLR3A-related disorders might be significantly different from that involved in ET and PD, for which the electrode placement has been optimized." (PMID 40248113, 2025).
varicella zoster virus infections (3 papers, 2019 to 2024). "The variant in POLR3A found in P15 is the same as that observed in P3 and his mother, both unvaccinated against SARS-CoV-2 and with mild COVID-19 and no previous varicella-zoster virus infection or any pathological predisposition to viral infectious diseases." (PMID 36880831, 2023).
4H leukodystrophy (2 papers, 2020 to 2022). "Their neurological presentation differs from classic 4H leukodystrophy, the initially described presentation of POLR3A variants." (PMID 31940116, 2020). "4H leukodystrophy, one of POLR3-related leukodystrophy, is a rare hereditary brain white matter disease caused by the pathogenic biallelic variations in POLR3A, POLR3B, or POLR1C." (PMID 36042647, 2022).
breast carcinoma (2 papers, 2020 to 2022). "—Downregulation of three (POLR3A, POLR3C, POLR3GL) catalytic components of RNA polymerase III, which synthesize small RNAs and were suggested as potential targets for breast cancer." (PMID 33302383, 2020).
hereditary spastic paraparesis (2 papers, 2020 to 2022). "We describe an Italian family with adult‐onset pure hereditary spastic paraplegia due to biallelic variants in POLR3A gene [c.1909 + 22G > A and c.3839dupT (p.M1280fs*20]." (PMID 33085208, 2020). "Our multimodal evaluation further expands the phenotypic spectrum associated with mutations in the POLR3A gene, in fact, for the first time, we describe an Italian family with a pure hereditary spastic paraplegia (SPG) and biallelic POLR3A variants." (PMID 33085208, 2020). "In conclusion, our data suggest that mutations of the POLR3A gene should be also considered among the cause of pure hereditary spastic paraparesis, further expanding the spectrum of phenotypes associated with mutations of this gene." (PMID 33085208, 2020).
Krabbe disease (2 papers, 2022 to 2023). A lysosomal disorder that affects the white matter of the central and peripheral nervous systems.